IL1B (interleukin 1 beta)
Diseases named in the same sentence as IL1B in open-access papers (continued):
Sharing a sentence is not in itself a finding about the gene and the disease.
silicosis (continued). "The mode by which IL-1β manipulates Th17 cell differentiation in silicosis remains unclear." (PMID 25091058, 2014). "IL-1β is a downstream product of NLRP3 inflammasome activation and has pro-inflammatory and fibrinogenic effects in silicosis." (PMID 38515835, 2024). "Among them, IL-1β, IL-6, TNF-α, and TGF-β1 have been identified as key pro-inflammatory and pro-fibrotic cytokines in silicosis." (PMID 39060930, 2024). "Subsequently, these macrophages undergo dysregulated polarization, with secretion of abundant cytokines such as IL-1β, IL-6, TNF-α, and TGF-β1, further promoting inflammation and progression of silicosis." (PMID 39060930, 2024). "The mRNA levels of Il-1β and Tnf-α as well as H&E staining revealed that GGA attenuated lung inflammation in the mouse model of silicosis." (PMID 38641226, 2024). "Our previous study suggested that blocking exosome secretion alleviated lung inflammation and decreased the expression of IL-1β, IL-6 and TNF-α in bronchoalveolar lavage fluid in mice with silicosis." (PMID 38454505, 2024). "Protein levels of IL-1β, IL-6, and TNF-α increased in the lungs of rats with silicosis and significantly decreased in YCF- and TET-treated rats." (PMID 37381044, 2023). "Since proinflammatory cytokines drive the progression of silicosis, we performed ELISA to measure the cytokine levels in the BALF and found the increased release of IL-1β and IL-18 in mice receiving intratracheal silica crystal suspension." (PMID 36131930, 2022). "AKEX0011 also significantly decreased the production of inflammatory factors such as TNF-α, IL-1β, IL-6, and TGF-β and the production of fibrosis markers such as collagen I, fibronectin, and α-SMA in silicosis." (PMID 35401236, 2022). "Knockout of RAB20 induced severe silicosis development by significantly promoting NLRP3 inflammasome activation and IL-1β release." (PMID 36131930, 2022). "Silica-stimulated macrophages activate pattern recognition receptors (PRRs) and NLRP3 inflammasome and release IL-1β, TNF-α, and interferons, which are the key mediators of silicosis pathogenesis." (PMID 36341426, 2022). "Western blot showed that the expression levels of IL-1β, IL-6, TNF-α and TGF-β1 in lung tissue from the silicosis group were significantly elevated." (PMID 35959439, 2022). "The secretion of TNF-α, IL-1β, IL-6, TGF-β1, and ox-LDL was significantly higher in the silicosis group than that in the HC group (p < 0.05)." (PMID 32351319, 2020). "RT‒PCR showed that inflammatory cytokines (IL-1β, IL-6 and TNF-α) were upregulated in AMs, but IL-10 expression was not significantly different, which indicated that AMs in the early stage of silicosis were mainly inflammatory macrophages." (PMID 38454505, 2024). "In addition, using a murine silicosis model, we show that the RAB20 knockout greatly promoted a crystalline silica-induced silicosis-like picture through enhancing the NLRP3 inflammasome activity and IL-1β release." (PMID 36131930, 2022). "FACS also suggested an augmented Th1 response in silicosis, but the connection between the Th1 response and IL-1β protein level was not obvious." (PMID 25091058, 2014). "Depletion of Tregs led to attenuated Th17 response in silicosis which suggested that Tregs could promote acute Th17 response and this function might depend on TGF-β1 and IL-1β." (PMID 22615967, 2012). "As inflammatory cytokines IL-6, IL-1β, TNF-α are also potent inducers of GM-CSF, it is not surprising that these cytokines are strongly associated with each other and act as predictors for silicosis patients." (PMID 36311760, 2022). "We also posit that the increasing expression of IL-6, IL-1β, IFN-γ and GM-CSF within silicotic individuals could be induced by early micro-granuloma development since it is a key mediator during acute phase response of silicosis." (PMID 36311760, 2022).
silicosis (continued). "Our findings observed that sRAGE were negatively correlated with TNF-α, IL-6, IL-1β, and ox-LDL (indicators of inflammation), but not TGF-β1 (indicator of fibrosis), suggesting that sRAGE might be an anti-inflammatory and not an antifibrotic marker in silicosis." (PMID 32351319, 2020).
tendinopathy (57 papers, 2014 to 2026). "It then examines recent advances in elucidating the pathogenetic roles and underlying mechanisms of IL-1β in tendinopathy." (PMID 41246304, 2025). "Interleukin-1 beta (IL-1β) has been implicated as an important mediator of the tissue inflammatory response of tendinopathy." (PMID 37759446, 2023). "As inflammation is an underlying mechanism of tendinopathy pathogenesis, mitochondrial transfer suppressed the levels of pro-inflammatory markers (IL-1β, IL-6, and TNF-α), revealing a promising therapeutic strategy against inflammatory." (PMID 37101277, 2023). "Inflammation is the primary pathogenic mechanism of tendinopathy, and mitochondrial transplantation suppressed NF-κB signaling along with pro-inflammatory marker (IL-1β and IL-6) levels." (PMID 33925007, 2021). "Notably, the proinflammatory cytokine interleukin-1β (IL-1β) has been implicated as a prominent mediator in the pathogenesis of tendinopathy." (PMID 41246304, 2025). "Since IL-1β is implicated in tendinopathy, IL-1RA may have therapeutic potential to improve tendon regeneration." (PMID 36543895, 2023). "Our data partially support this hypothesis, given the negative relationships observed between AT CSA and pro-inflammatory cytokines TNF-α, IL-6 and IL-1β, all have been associated with the development of tendon disorders." (PMID 33484409, 2021). "The inflammatory cytokines IL-6 and IL-1β have been implicated in tendinopathies." (PMID 32095779, 2019). "In rats, the tendinopathy-associated proinflammatory cytokine IL-1β downregulates the expression of miR-337-3p, and miR-337-3p administration may accelerate tendon healing via the modulation of chondro-osteogenic and tenogenic differentiation balance of tendon progenitors." (PMID 32290510, 2020). "Although earlier studies suggested that FD facilitates IL‐1β–driven p65 polyubiquitination and degradation in tendinopathy, our data showed that blocking ubiquitination with MLN7243 did not prevent FD‐mediated degradation of p65." (PMID 41503854, 2026). "In the context of tendinopathy, IL-1β promotes MMP3 expression by activating the MAPK/NF-κB pathway, whereas TGF-β1 exerts anti-degradation effects by suppressing this pathway." (PMID 40918434, 2025). "In summary, the impact of IL-1β on TSPCs represents a critical paradigm shift in tendinopathy pathogenesis." (PMID 41246304, 2025). "Proinflammatory cytokines such as IL-1β are recognized as primary initiators of tendinopathy and can be released by tenocytes in response to mechanical overload." (PMID 41383714, 2025). "This review synthesizes current understanding of IL-1β synthesis and its downstream signaling transduction pathways, with the primary objective of elucidating the mechanisms by which IL-1β contributes to tendinopathy progression." (PMID 41246304, 2025). "Collectively, IL-1β is a critical node connecting the three cellular compartments and driving chronic inflammation in tendinopathy." (PMID 41246304, 2025). "Beyond its well-characterized roles in promoting inflammation and matrix degradation, IL-1β contributes to tendinopathy pathogenesis by accelerating tenocyte death through the induction of apoptotic pathways." (PMID 41246304, 2025). "Perhaps the most significant advance in understanding IL-1β’s role in tendinopathy lies in its integration with the condition’s biomechanical etiology." (PMID 41246304, 2025). "Further investigation is nevertheless essential to fully delineate the precise actions of IL-1β in tendinopathy." (PMID 41246304, 2025). "Articles were included if the topic is related to IL-1β or tendinopathy, and the article type was a review or experimental paper." (PMID 41246304, 2025). "Collectively, these studies firmly establish IL-1β as a master regulator of ECM degradation in tendinopathy, primarily by disrupting the critical balance between MMPs and TIMPs." (PMID 41246304, 2025).
tendinopathy (continued). "Interleukin-1β (IL-1β), a prototypical proinflammatory cytokine, plays a critical role in the pathogenesis of tendinopathy." (PMID 41246304, 2025). "Although direct crosstalk between YAP and IL-1β in tendinopathy remains underexplored, studies in other musculoskeletal tissues suggest that YAP signaling can modulate IL-1β production and subsequent MMP activation." (PMID 41246304, 2025). "By integrating these insights, this review seeks to deepen the mechanistic understanding of tendinopathy and facilitate the development of targeted therapies, thereby reinforcing the rationale for IL-1β as a therapeutic target." (PMID 41246304, 2025). "Second, although in vitro models of tendinopathy using IL-1β treatment are widely adopted, their ability to accurately reproduce clinical tendinopathy remains questionable." (PMID 39500862, 2024). "To identify the profile of various types of GFs secreted by smumf cells co-culture at P10 under an IL-1β-induced tendinopathy environment, we conducted a human growth factor array analysis using co-cultured supernatant." (PMID 39500862, 2024). "IL-1β, which is overexpressed in clinical samples of tendinopathy, reduced the expression of tenogenic markers but increased the expression of nontenogenic markers in TDSCs." (PMID 38612656, 2024). "Diseased tendon stromal fibroblasts isolated from patients with tendinopathy were found to exhibit more profound induction of inflammatory markers compared to healthy tendon stromal fibroblasts upon IL-1β treatment." (PMID 38612656, 2024). "IL-1β, a prominent pro-inflammatory cytokine frequently present in tendon disorders, was employed to simulate the tendinopathy environment." (PMID 39500862, 2024). "In this study, we found that NLRP3 controls the production of IL-1β in a mouse model of tendinopathy by sterile extracellular matrix degradation, while an alternative ASC-dependent inflammasome controls IL-18 production." (PMID 39468985, 2024). "Tenocytes are a key type of cell influenced by tendinopathy, and IL-1β was adopted to mimic the pathological status and inspect the protective effects of EVs derived from ADMSCs." (PMID 36604715, 2023). "Of course, we have discussed the similarities and differences between supplementing TNF and IL-1β in tendinopathy inflammation for the reviewer's reading." (PMID 37600349, 2023). "Most studies agree that IL-1b is directly positively correlated to the degree of pain in patients with RC tendinopathy, especially when the examined sample is taken from the subacromial bursa." (PMID 35892325, 2022). "qRT-PCR results showed that the expression of inflammatory cytokines Il-1b, Il-6 and Tnfa significantly increased during tendinopathy, and this enhancement was reversed by FR treatment in the CIT group." (PMID 35458235, 2022). "It is reported that IL-1β is highly expressed in tendinopathy, which is a key inflammatory mediator to mediate the inflammatory reaction and accelerate tendinopathy." (PMID 35458235, 2022). "A number of investigators have demonstrated that proinflammatory mediators such as interleukin 1β (IL-1β) initiate fibrosis, extracellular matrix degradation, and apoptosis, eventually leading to tendinopathy." (PMID 34306308, 2021). "While senescence appeared in the tendinopathy process, these results showed that SP obtained a fairly good antisenescence function on TDSCs in vitro IL-1β-induced tendinopathy model." (PMID 34306308, 2021). "We used IL-1β and TNF-α, two hallmark cytokines of inflammation in tendons, which are associated with tendon injury and tendinopathy in vivo and in vitro, to induce disease-relevant inflammation." (PMID 34127759, 2021). "The evidence from animal studies thus supports the role of IL-1β in the pathogenesis and progression of tendinopathy." (PMID 34863223, 2021).
tendinopathy (continued). "A systematic review of cytokines in tendon disease reported that the expression of IL-1β, IL-6, and TNF-α in animal tendon injury models tended to increase from the early phase of tendon healing." (PMID 34090401, 2021). "IL-1β is a typical proinflammatory cytokine known to play a role in tendon disorders such as tendinopathy." (PMID 32545914, 2020). "More specifically, in this study, we found that the proinflammatory cytokine IL-1β downregulates the expression of miR-337-3p; the IL-1β/miR-337-3p axis-mediated pathogenesis of tendinopathy is identical in both models." (PMID 31065679, 2020). "We subsequently stimulated AT and AR cells with IL-1β because it is known to induce expression of NF-κB target genes highly expressed in human tendon disease, therefore recapitulating an inflammatory milieu." (PMID 30916999, 2019). "Tendon stromal cells were stimulated with IL-1β because it is known to induce expression of NF-κB target genes highly expressed in human tendon disease, simulating an inflammatory environment." (PMID 31437425, 2019). "Using cultures of tendon-derived stromal cells from healthy donors and patients with tendinopathy, we next investigated differences in prostaglandin profiles between healthy and diseased cells before and after treatment with IL-1β (10 ng/mL)." (PMID 30867043, 2019). "Others21, 23 have reported significantly elevated MMP-1 and -3 expression after IL-1β stimulation in human tendon cells and have made IL-1β a candidate for an in vitro tendinopathy model." (PMID 28091588, 2017). "IL-1β, a proinflammatory cytokine, has been proposed as the initiator of tendinopathy because it induces inflammation, apoptosis, and ECM degradation by activating MMPs20." (PMID 28091588, 2017). "Whilst genetic variants in IL1β (rs1143627 and rs16944) have been implicated to an increase in IL1β gene expression, interleukin-6 (IL6) was found to be linked to tenocyte apoptosis, which is a characteristic of tendinopathy." (PMID 28523640, 2017). "This included finding lower levels of TNF-α (and a lower level in PDGF-BB and a trend for a decrease in IL-1β) in the female tendinopathy group, as compared to the control female group." (PMID 26925234, 2016). "A lowering in PDGF-BB and a trend for a decrease in IL-1β was also seen in the female tendinopathy group, when compared to the female control group." (PMID 26925234, 2016). "As macrophages are the primary source of IL-1β and TNFα and this cell type has been identified in various tendinopathy and tendon healing models, we developed a more biologically relevant co-culture in vitro model for the current study." (PMID 25889287, 2015). "This study demonstrates that IL-1β mimics some aspects of tendinopathies with PGE2 induction, MMP expression (mostly MMP1 and MMP3), and increases of type III/I collagen ratio." (PMID 26156631, 2015). "This work shows that CIP has moderate effects on tendon cells, compared to IL-1β, suggesting that IL-1β treatment is a better model to mimic tendinopathies in vitro (with an increase of MMPs, PGE2 and type III collagen expression) than CIP." (PMID 26156631, 2015). "The aim of this study was to identify COMP fragments generated at different stages of tendon disease and to relate these to those induced specifically by IL-1β and PGE2in vitro." (PMID 24398684, 2014). "Once outside the cell, IL-1β can bind to its cognate receptors on neighboring cells, initiating and amplifying pro-inflammatory signaling cascades that contribute to the pathogenesis of tendinopathy and other inflammatory conditions." (PMID 41246304, 2025). "However, a comprehensive understanding of the mechanisms through which IL-1β contributes to tendinopathy remains incomplete, hindering the translation of these findings into clinical applications." (PMID 41246304, 2025). "Consequently, further research is essential to delineate the precise mechanisms of IL-1β involvement in tendinopathy." (PMID 41246304, 2025).
tendinopathy (continued). "IL-1β is one of the key factors contributing to the development of tendon disorders." (PMID 40873435, 2025). "Future therapeutic strategies could focus on targeting this cytokine network, particularly disrupting the chronic inflammatory state maintained by the IL-1β/NF-κB axis, potentially offering new avenues for the fundamental treatment of tendinopathy." (PMID 41246304, 2025). "Therapeutic strategies aimed at selectively eliminating senescent cells (senolytics) or modulating their secretory phenotype (senomorphics) may therefore hold promise for disrupting this vicious cycle in IL-1β-driven tendinopathy." (PMID 41246304, 2025). "In tendinopathies, an imbalance favoring type I inflammation, exacerbated by IL-1b, may worsen tissue properties by inducing leukocyte infiltration and matrix metalloproteinases, leading to extracellular matrix degradation and tear development." (PMID 38731971, 2024). "Diseased tendon stromal fibroblasts isolated from patients with tendinopathy exhibited more profound induction of inflammatory markers compared to healthy cells after IL-1β stimulation, a treatment commonly used to mimic overuse-induced inflammation in tendons." (PMID 38612656, 2024). "In conclusion, our results revealed the two formulations, cHA (50:50) + DEX and cHA (20:80) + DEX, ameliorate tendinopathy via anti-apoptotic and anti-senescent effects in IL-1β-stimulated tendinopathic tenocytes and a rat collagenase-induced tendinopathy model." (PMID 36077161, 2022). "In this study, we used three specific formulations of cHA + DEX to treat IL-1β-stimulated primary human tenocytes and the experimental rat tendinopathy model to test our hypothesis." (PMID 36077161, 2022). "In clinical samples of tendinopathy, the presence of IL1β is ambiguous." (PMID 34350166, 2021). "Other researchers proposed that pro-inflammatory cytokines, such as IL-1β could initiate tendinopathies by stimulating inflammation, apoptosis, and extracellular matrix degradation." (PMID 33683459, 2021). "Indeed, IL-1β, which is recognized as the initiator of tendinopathy since it induces inflammation, apoptosis, and ECM degradation by activating MMPs, drastically dropped out after HA treatment." (PMID 33807327, 2021). "Future studies addressing whether the diminished tissue expression of active ERK1/2 and the increased IL-1β-induced activation is related to aging or represents end-stage tendon disease is warranted." (PMID 31831776, 2019). "IL-1β is a major cytokine that induces catabolic action on tendon fibroblasts via the upregulation of inflammatory mediators and plays a role in the tendon’s degenerative changes in tendinopathy or regenerative capacity." (PMID 31791360, 2019). "This in vitro model shows that mechanical stimulation and IL-1β may mediate markers of tendinopathy." (PMID 32095779, 2019). "The proinflammatory cytokine IL-1β has been considered as an initiator of tendinopathy." (PMID 30296306, 2018). "Similarly, in incubations with cells from tendinopathy patients, IL-1β and MaR1 (10 nM) we found elevated concentrations of the MaR1 metabolite 14-oxo-MaR1 compared to healthy cells incubated with IL-1β and MaR1 (p = 0.01)." (PMID 28887458, 2017). "As IL-1β induces NF-κB target genes known to be highly expressed in early-stage tendinopathy, we further investigated if IL-1β treatment of cultured tendon cells induces persistent stromal fibroblast activation, and if this response differs between healthy and diseased cells." (PMID 28122639, 2017). "A trend was seen for lower IL-1β in the female tendinopathy group." (PMID 26925234, 2016). "Indeed, pro-inflammatory cytokines such as IL-1β have been identified as the main initiators of tendinopathy, stimulating inflammation, apoptosis and matrix degradation." (PMID 26156631, 2015). "Therefore, our results confirm that in tendinopathies, differential IL-1β and IL-18 production could be controlled by different inflammasomes." (PMID 39468985, 2024).